ZNF582 (zinc finger protein 582)
Description:
May be involved in transcriptional regulation.
Synonyms: FLJ30927
Tractability: PROTAC: ubiquitination databases record sites on it.
Gene: Protein-coding gene on chromosome 19 (56,375,846 to 56,393,538, reverse strand). Ensembl gene ENSG00000018869.
Subcellular location: Nucleus
Subcellular location (Human Protein Atlas): Cytosol; Nucleoplasm
Pathways (Reactome):
Gene expression (Transcription): Generic Transcription Pathway
Gene Ontology:
Molecular function: protein binding; DNA-binding transcription factor activity, RNA polymerase II-specific; RNA polymerase II transcription regulatory region sequence-specific DNA binding; DNA binding
Biological process: regulation of transcription by RNA polymerase II; regulation of DNA-templated transcription
Cellular component: nucleus
Genetic constraint (gnomAD): Loss-of-function variants: 14 observed, 13.07 expected, observed/expected ratio (o/e) 1.07, 90% interval 0.71 to 1.65. The upper end of that interval is the gene's LOEUF score, 1.65, which puts it in group 6 of 6, group 1 being the genes least tolerant of losing a copy. Missense variants: 567 observed, 645.75 expected, observed/expected ratio (o/e) 0.88, 90% interval 0.82 to 0.94. Synonymous variants: 210 observed, 218.82 expected, observed/expected ratio (o/e) 0.96, 90% interval 0.86 to 1.08.
Homologues: Orthologues: chimpanzee ZNF582 (99% identical), macaque ZNF582 (96% identical), rabbit ZNF582 (85% identical), mouse Zfp582 (71% identical), Drosophila melanogaster CG3281 (26% identical), Drosophila melanogaster CG2712 (22% identical), Drosophila melanogaster Phs (22% identical). Paralogues in human: ZNF566 (48% identical), ZNF529 (46% identical), ZNF404 (45% identical), ZNF805 (44% identical), ZNF264 (43% identical), ZNF599 (43% identical), ZNF614 (42% identical), ZNF25 (42% identical), ZFP37 (42% identical), ZFP90 (40% identical), ZNF555 (39% identical), ZNF674 (39% identical), and 50 more.
Diseases named in the same sentence as ZNF582 in open-access papers:
ZNF582 is named in the same sentence as 31 diseases in open-access papers, as found by Europe PMC text mining. Sharing a sentence is not in itself a finding about the gene and the disease. The quoted sentences say what the papers report.
cervical carcinoma (17 papers, 2012 to 2025). A carcinoma arising from either the exocervical squamous epithelium or the endocervical glandular epithelium. "ZNF582 methylation is another confirmed marker associated with cervical cancer, and ZNF582 methylation has also been reported as a potential marker for EC detection in tissue samples, although the study of ZNF582 methylation in plasma samples is insufficient." (PMID 37867599, 2023). "Recently, methylated zinc finger protein 582 (ZNF582) (ZNF582m) was reported to be highly associated with cervical cancer." (PMID 25945131, 2015). "In conclusion, the ZNF582 methylation test represents a significant advancement in cervical cancer triage." (PMID 41458485, 2025). "Various types of DNA methylation, such as those involving PAX1, ZNF582, and FAM19A4, are strongly linked to CINs and cervical cancer." (PMID 40291776, 2025). "ZNF582 methylation (ZNF582m) test has been identified as a highly promising biomarker for the detection of cervical cancer and its precursor lesions." (PMID 41458485, 2025). "For instance, ZNF582 exhibits high methylation levels in GC and cervical cancers, while TFPI2 displays elevated methylation in GC and CRC." (PMID 38774285, 2024). "It has been suggested that the overexpression of ZNF582 can induce cell cycle arrest at the S/G2 phase in cervical cancer cells treated with radiotherapy." (PMID 38651153, 2024). "The overexpression of ZNF582 protein reinforced the tolerance of cervical carcinoma cells towards chemotherapy and radiation.In a previous study, it was reported that ZNF582 methylation was detected in 100% of squamous cell carcinoma tissues." (PMID 38651153, 2024). "Previously, the frequent silencing of ZNF582 by methylation in cervical cancers was demonstrated, alongside its potential use for detecting cervical pre-cancerous lesions." (PMID 39408131, 2024). "ZNF582 methylation status has been demonstrated as a good biomarker for cervical cancer induced by HPV, with a sensitivity of 73% and a specificity of 80%." (PMID 31316555, 2019). "A high frequency of promoter methylation of PAX1 and ZNF582 genes has been detected in cervical cancer." (PMID 28241446, 2017). "Promoter hypermethylation of ADCY8, CDH8, and ZNF582 was corroborated in five cervical cancer cell lines with two exceptions." (PMID 27651839, 2016). "Promoter methylation of ADCY8, CDH8, and ZNF582 was markedly elevated across all four stages of cervical carcinoma." (PMID 27651839, 2016). "In conclusion, we identified ZNF582 as a potential candidate gene in the development of a novel strategy for molecular cervical cancer screening." (PMID 22815913, 2012). "The present study has identified, for the first time, the hypermethylated gene, ZNF582, with possible utility in the molecular detection of cervical cancer." (PMID 22815913, 2012). "Moreover, quantitative detection of ZNF582 methylation contributes to the diagnosis of clinical cervical cancer." (PMID 36966163, 2023). "Previous studies have demonstrated that the methylation status of PAX1/ZNF582 may serve as useful biomarkers for the detection of cervical cancer." (PMID 28241446, 2017). "Although the biological function of ZNF582 is not yet well characterized, a group in Taiwan found similar associations for cervical cancer and adenocarcinoma with ZNF582 using cervical scrapings." (PMID 25945131, 2015). "Further investigation of the functional role of ZNF582 in cervical cancer may provide more biological insight in cancer biology." (PMID 22815913, 2012). "In the market, there are also two CE-marked tests for the detection of cervical cancer (Cervi-M®) and oral cancer (Oral-M®) by analyzing PAX1 and ZNF582 gene methylation in cervix smears and oral epithelial cells." (PMID 37511475, 2023). "Algorithms that include molecular tests (methylated PAX1, ZNF582, and HPV16/18) in combination with clinical examination findings provide an effective method to increase the accuracy of diagnosis for cervical cancer." (PMID 27293491, 2016).
cervical carcinoma (continued). "Our study shows ZNF582 is frequently methylated in CIN3 and worse lesions, and it is demonstrated as a potential biomarker for the molecular screening of cervical cancer." (PMID 22815913, 2012). "TCGA data for the cervical cancer cohort (N = 231) revealed distinct hypermethylation patterns among ADCY8, ZNF582, and CDH8 for reported and non-reported clinical stages (median β value range, 0.427–0.632)." (PMID 27651839, 2016).
oral cancer (6 papers, 2019 to 2025). "Hypermethylated PAX1 and ZNF582 are effective biomarkers for detecting oral cancer and oral dysplasia, and for predicting the recurrence of oral cancer." (PMID 40256126, 2025). "Previous reports have found the hypermethylation of ZNF582 in a variety of tumors, including cervical neoplasm, esophageal squamous cell carcinoma, oral cancer, nasopharyngeal carcinoma." (PMID 36966163, 2023). "ZNF582 methylation demonstrated as an effective biomarker for the detection of oral dysplasia and oral cancer via collection of oral scrapings from normal oral mucosa subjects, oral potentially malignant patients, and OSCC patients." (PMID 35885450, 2022). "The correlation between ZNF582 methylation and oral cancer has been extensively studied in recent years." (PMID 35885450, 2022). "ZNF582 and PAX1 were initially selected from a multi-gene panel of SCC type cancers that included ZNF582, PAX1, SOX1, NKX6.1, and PTPRR genes; these were later developed into a methodology using oral scrapings for the detection of oral dysplasia and oral cancer." (PMID 34359370, 2021).
nasopharyngeal carcinoma (4 papers, 2021 to 2023). A carcinoma arising from the nasopharyngeal epithelium. "The hypermetylation of ZNF582 in nasopharyngeal carcinoma (NPC) is associated with higher migration, invasion, and metastasis." (PMID 36553083, 2022). "Interestingly, hypermethylation of ZNF582, the same class as zinc finger protein associated with L-leucine in our research, regulated the transcription of NRXN3 in nasopharyngeal carcinoma." (PMID 38049855, 2023).
squamous cell carcinoma (4 papers, 2017 to 2024). A carcinoma arising from squamous epithelial cells. "Combined with HPV-16/18 genotyping, both a dual methylation test for PAX1/ZNF582 and testing for ZNF582 methylation demonstrated 100% association of methylation with pathology results, indicating carcinoma in situ or squamous cell carcinoma." (PMID 28977944, 2017). "ZNF582 promoter hypermethylation has been confirmed in multiple of studies of cervical precancerous lesions, and invasive adeno- and squamous carcinomas." (PMID 33178175, 2020).
acute myeloid leukemia (3 papers, 2012 to 2024). Acute myeloid leukemia (AML) is a group of neoplasms arising from precursor cells committed to the myeloid cell-line differentiation. "Consistent with the concept that ZNF582 is a tumor suppressor, ZNF582 hypermethylation has been reported in acute myeloid leukemia and various invasive cancers." (PMID 28241446, 2017). "A recent study of acute myeloid leukemia revealed that ZNF582 is consistently aberrantly methylated in different disease subtypes." (PMID 22815913, 2012). "We select six representative genes from CancerMine, which include three most frequently reported genes in the context of acute myeloid leukemia (AML), KMT2A, FLT3, and MLLT3, as well as three genes that are least reported in this specific cancer, namely ZFP36L2, ZIC2, and ZNF582." (PMID 38431735, 2024).
anal carcinoma (3 papers, 2021 to 2025). "A cross‐sectional series of 176 tissue samples of anal cancer, AIN3, AIN2, AIN1 and control biopsies obtained in HIV‐negative women and men was tested for six methylation markers (ASCL1, LHX8, SST, WDR17, ZIC1 and ZNF582)." (PMID 33580586, 2021). "We recently validated that particularly the marker combinations ASCL1 and ZNF582, either or not combined with SST, had a very good performance for AIN3 and anal cancer detection in MSM living with HIV and a similarly good performance to detect AIN3 and cancer in HIV‐negative MSM." (PMID 40400293, 2025).
cervical intraepithelial neoplasia (3 papers, 2015 to 2020). "The differences in the methylation statuses of three genes, PAX1, SOX1, and ZNF582, were evident between normal control samples and cervical intraepithelial neoplasm (CIN) I–III as well as SCC samples." (PMID 33003642, 2020). "Several studies examining paired boxed gene 1 (PAX1) and zinc finger protein 582 (ZNF582) have reported their potential utilization as highly sensitive biomarkers for detection of cervical intraepithelial neoplasia at grade 3 or higher (CIN3+)." (PMID 27293491, 2016). "Recently, one study also revealed that hypermethylated ZNF582 (methylated ZNF582 (ZNF582m)) performs well as a marker for detecting grade III or higher cervical intraepithelial neoplasia (CIN3+) with 73% sensitivity and 71% specificity for women with low-grade squamous intraepithelial lesions." (PMID 25945131, 2015). "The delta Cp of methylated PAX1 and ZNF582 was obtained via quantitative methylation-specific PCR in a training set (57 CIN2− and 43 cervical intraepithelial neoplasia ≥grade 3 (CIN3+) women), and the individual and combination gene sensitivities and specificities were determined." (PMID 27293491, 2016).
esophageal cancer (3 papers, 2017 to 2023). A primary or metastatic malignant neoplasm involving the esophagus. "The methylation of PAX1 and ZNF582 detected in these cells could act as biomarkers for esophageal cancer screening in the future, which could replace traditional endoscopy as an equally effective but less invasive way of diagnosing for esophageal cancer." (PMID 28241446, 2017). "However, whether the promoter methylation status of the PAX1 and ZNF582 genes is associated with ESCC and could be novel biomarkers for early esophageal cancer detection remains to be elucidated." (PMID 28241446, 2017). "Similarly, ZNF582 and ZNF569 showed high methylation in esophageal cancers, and RASSF1A has been approved by NMPA as a lung cancer early detection marker." (PMID 37560387, 2023).
esophageal squamous cell carcinoma (3 papers, 2017 to 2023). Esophageal squamous cell carcinoma (ESCC) is a type of esophageal carcinoma (EC) that can affect any part of the esophagus, but is usually located in the upper or middle third. "In Esophageal Squamous Cell Carcinoma (ESCC), aberrant hypermethylation of ZNF582 and PAX1 have been demonstrated using quantitative methylation-specific PCR with levels at 21% versus 0% for tumor and peri-tumor normal tissues, respectively." (PMID 33178175, 2020). "In the present study, we investigated the methylation status of PAX1 and ZNF582 genes in esophageal squamous cell carcinoma (ESCC) tissues." (PMID 28241446, 2017).
carcinoma in situ (2 papers, 2012 to 2017). "Although protein expression in carcinoma in situ is high, we detected the DNA methylation of ZNF582, that indicated the molecular propensity of some in situ cells toward cancer invasion." (PMID 22815913, 2012).
Cervical (2 papers, 2012 to 2024). "In this study, we evaluated the relationship between cervical lesions with various histopathological characteristics and p16/ki67 immunohistochemical staining and PAX1/ZNF582 methylation in high-risk HPV-positive women." (PMID 39304838, 2024). "In this study, we evaluated the relationship between cervical lesions with various histopathological characteristics and p16/ki67 immunohistochemical staining and PAX1/ZNF582 methylation in HR-HPV-positive women." (PMID 39304838, 2024). "The primary strength of this study was the inclusion of different grades of cervical lesions, i.e., cervicitis, CIN1, CIN2, CIN3, and cervical SCC, enabling a comprehensive analysis of the relationship among PAX1/ZNF582 methylation, p16/Ki67 immunohistochemical scores, and cervical lesions." (PMID 39304838, 2024).
oral squamous cell carcinoma (2 papers, 2017 to 2026). "Previous studies have shown that the methylation status of PAX1 and ZNF582 genes is a useful testing to distinguish tumor and non-tumor tissues in cervical and oral squamous cell carcinoma." (PMID 28241446, 2017).
and adenocarcinoma of the cervix (1 paper, 2016). "Previous studies have shown that ZNF582 is frequently methylated in invasive squamous and adenocarcinoma of the cervix, as well as preinvasive disease." (PMID 27651839, 2016).
cervical neoplasm (1 paper, 2015). "In this study, we analyzed the concordance and clinical performance of DNA methylation biomarker (PAX1, SOX1, and ZNF582) detection in self-collected vaginal samples and physician-collected cervical samples for the identification of cervical neoplasm." (PMID 25985991, 2015). "The clinical performance of PAX1, SOX1, and ZNF582 as biomarkers of cervical neoplasm has been validated in multi-center clinical trials; therefore, analysis of changes in the methylation status of these genes could be applied for self-collected vaginal samples." (PMID 25985991, 2015).
clear cell renal cell carcinoma (1 paper, 2023). "Recent evidences have suggested that Zinc finger protein 582 (ZNF582) plays different important roles in various tumors, but its clinical role, biological function and regulatory mechanism in clear cell renal cell carcinoma (ccRCC) are still vague." (PMID 36966163, 2023).
Hyperkeratosis (1 paper, 2024). Hyperkeratosis is a histopathological term defining a thickened stratum corneum and may be present in many different skin conditions, with many possible overlaps. "The gene methylation panel based on ZNF582 and PAX1 yielded a sensitivity ranging from 31% for hyperplasia/hyperkeratosis to 90% for moderate dysplasia oral lesions." (PMID 39138540, 2024).
invasive carcinoma (1 paper, 2020). A carcinoma that is not confined to the epithelium, and has spread to the surrounding stroma. "Finally, in a Netherlands study of 345 anal intraepithelial neoplasia (AIN grades 1-3) and invasive carcinoma samples, ZNF582 methylation levels escalated with increased disease severity." (PMID 33178175, 2020).
kidney tumors (1 paper, 2023). "Using cell phenotype experiments and orthotopic kidney tumor growth models, we determined the inhibitory effect of ZNF582 overexpression on ccRCC growth and metastasis in vivo and in vitro." (PMID 36966163, 2023). "Using Immunofluorescence EdU and TUNEL method, clone formation experiment, wound healing assay, cell migration and invasion experiments and orthotopic kidney tumor growth model, we verified the inhibitory effect of ZNF582 overexpression on ccRCC growth and metastasis in vitro and in vivo." (PMID 36966163, 2023).
lymph node metastasis (1 paper, 2017). "However, there is a tendency that PAX1 methylation level was associated with TNM stage and lymph node metastasis with a p value of 0.068 and 0.073, respectively, while ZNF582 methylation level was associated with carcino-embryonic antigen (CEA) concentration with a p value of 0.076." (PMID 28241446, 2017).